RUNX1 (RUNX family transcription factor 1)
Diseases named in the same sentence as RUNX1 in open-access papers (continued):
Sharing a sentence is not in itself a finding about the gene and the disease.
neuroblastoma (14 papers, 2012 to 2025). Neuroblastoma (NB) is the most common solid, extracranial childhood tumor. "In contrast, RUNX1 overexpression has been linked to favorable outcomes and monitored prognosis during therapy in neuroblastoma." (PMID 35534796, 2022). "Interestingly, Itch can also facilitate proteasomal degradation of ΔNp63, indicating that RUNX1 deficiency in neuroblastomas may contribute to cell proliferation also through stabilization of ΔNp63." (PMID 36831211, 2023). "Therefore, functional interruption of RUNX1 that is causally related to stabilization of TAp63 may potentially contribute to preventing MYCN-driven cell proliferation of neuroblastoma." (PMID 36831211, 2023). "In contrast, RUNX1-mediated downregulation of TrkA and TrkC implies that RUNX1 has oncogenic potential in neuroblastomas." (PMID 36831211, 2023). "Conditioned media obtained from RUNX1-silenced neuroblastoma cells has been shown to stimulate in vitro tube formation in human umbilical vascular endothelial cells (HUVECs)." (PMID 36231060, 2022). "Intriguingly, in neuroblastoma, RUNX1 exhibits elevated expression levels in benign ganglioneuromas (GN) and well-differentiated tissues, while displaying reduced expression in poorly differentiated and undifferentiated tissues, suggesting its tumor-suppressive role in neuroblastoma." (PMID 38430423, 2024). "Further investigation of targeting RUNX1 may be advantageous as a potential therapeutic strategy for neuroblastoma." (PMID 36831211, 2023). "Notably, studies on the roles of p73 and p63 have highlighted a possible function of RUNX1 in regulating neuroblastoma cell proliferation." (PMID 36831211, 2023). "Moreover, athymic nude mice bearing xenografts formed by subcutaneous injection of neuroblastoma SH-SY5Y cells stably expressing RUNX1 or short hairpin RNAs of RUNX1 display inhibited or accelerated tumor development, respectively." (PMID 36831211, 2023). "In addition, the SH-SY5Y and SK-N-SH neuroblastoma cells subjected to RUNX1 knockdown demonstrate increased microvessel density in xenograft tumor tissues." (PMID 36231060, 2022). "Comparable to amplification of MYCN in childhood neuroblastomas, iAMP21 including AML1/RUNX1 is discussed to be an initial event in the development of leukemic blasts comprising this genomic lesion, and no information exists that AFS change over time within these cells." (PMID 23210797, 2012). "Therefore, in contrast to RUNX3, RUNX1, together with the RUNX1-mediated decrease in TrkA and TrkC, may be essential for neuroblastoma proliferation, especially in neuroblastomas with the 1p36 deletion." (PMID 36831211, 2023).
neuroblastoma (continued). "The HSV-1 genome is enriched for binding-sites of RUNX1 and binding of overexpressed RUNX1 prevents HSV-1 gene expression and lytic replication in an in vitro model of HSV-1 in neuroblastoma cells." (PMID 37876935, 2023). "However, in primary neuroblastomas, RUNX3 acts as a tumor-suppressor, whereas RUNX1 bifunctionally regulates cell proliferation according to the characterized genetic and epigenetic backgrounds, including MYCN oncogenesis." (PMID 36831211, 2023).
triple-negative breast carcinoma (14 papers, 2013 to 2025). An invasive breast carcinoma which is negative for expression of estrogen receptor (ER), progesterone receptor (PR), and human epidermal growth factor receptor 2 (HER2). "The results showed that similar to the effects of RUNX1 expression in luminal cancers, elevated expression of DDR1 associated with increased survival in non-triple negative breast cancers (ER+/PR+/HER2+) (Figures 6Ci and 6Cii)." (PMID 40614729, 2025). "In contrast, it has also been shown that RUNX1 levels are abnormally elevated in triple-negative breast cancer (TNBC) and this is associated with a poor prognosis, indicating that RUNX1 plays a pro-tumor role in TNBC." (PMID 38430423, 2024). "In a previous study, RUNX1 was found to collaborate with the androgen receptor in triple-negative breast cancer CSCs to promote cancer recurrence after chemotherapy, whereas inhibition of RUNX1 transcriptional activity reduced expression of CSC marker genes." (PMID 39107908, 2024). "They showed that high Runx1 protein expression correlated with poor prognosis in triple negative breast cancer patients." (PMID 26735887, 2016). "We envisage that future studies, using in vivo triple-negative breast cancer models will help to clarify the role of RUNX1 and RUNX2 in triple-negative breast cancer." (PMID 26489514, 2015). "Conversely, there is evidence of RUNX1 over-expression in various cases of ER negative and triple negative breast cancer, supporting a pro-oncogenic role of RUNX1 correlated with poor prognosis and survival." (PMID 36831308, 2023).
psoriasis (12 papers, 2009 to 2024). An autoimmune condition characterized by red, well-delineated plaques with silvery scales that are usually on the extensor surfaces and scalp. "IL-17 receptors, RUNX1, and IL-21 with miR-215-binding UTRs constitute Th17 subset-specific signature molecules, implying the potential role of miR-215 in psoriasis-associated Th17 dysregulation." (PMID 37700769, 2023). "RUNX1 expression is downregulated in psoriasis, and underexpression in the liver is a marker of metastasis." (PMID 38397136, 2024). "From a pathological aspect, a genome-wide association study (GWAS) suggested the possible involvement of Runx1 and Runx3 in psoriasis, an abnormal manifestation of keratinocyte proliferation and differentiation." (PMID 36077435, 2022). "Further, pDCs are associated with skin autoimmune conditions, which raises the possibility that the aberrant activation of pDCs may be contributing to the high incidence of eczema and psoriasis observed in RUNX1-FPD patients." (PMID 37581927, 2023).
breast tumors (11 papers, 2010 to 2023). "Analyses of breast tumors and patient data revealed that low Runx1 expression is associated with poor prognosis and decreased survival." (PMID 28407681, 2017). "Downregulation of RUNX1 was specifically noted in metastatic breast cancers, and attenuated expression of RUNX1 protein was reported in high-grade breast tumors when compared to low or mild-grade tumors." (PMID 36831308, 2023). "Collectively, these data provide evidence of a new mechanism for breast tumor gene expression regulation, in which Runx1 and Foxp3 physically interact to control mammary epithelial cell gene expression fate." (PMID 26735887, 2016). "Other authors also described this controversy analyzing RUNX1 expression by different techniques in human breast tumor samples." (PMID 26735887, 2016). "One study showed that when breast tumor cells expressing RE (RE+) were exposed to β-estradiol, they showed lower expression of MB, possibly via regulation of RUNX1, one of the transcription factors observed to be differentially expressed in the present study and which regulates this set of genes." (PMID 36982287, 2023). "Thus, the decreased Runx1 in human samples with increased disease progression indicates Runx1 has distinct functional activities that differ between mouse and human breast tumors." (PMID 28407681, 2017). "To achieve this goal, we investigated Runx1 and Foxp3 participation in the regulation of expression of two tumor associated genes, Rspo3 and GJA1, which are known modulators of breast tumor cell growth (positively and negatively, respectively)." (PMID 26735887, 2016). "Our work suggests for the first time that Runx1 could be involved in breast tumor progression depending on Foxp3 availability." (PMID 26735887, 2016). "Furthermore, we found that RUNX1 expression was reduced in high-grade primary breast tumors compared to low/mid-grade tumors." (PMID 20169162, 2010). "Emerging data indicates that Runx1 could be relevant for breast tumor promotion." (PMID 26735887, 2016). "We found that most breast tumors had much lower expression of TAp73, CBFB, and RUNX1 compared to adjacent normal breast tissues." (PMID 33945523, 2021). "Recent evidence also suggests that the transcription factor FOXP3 directly binds to and inhibits RUNX1 in mammary epithelial cells, whereas in the absence of FOXP3 in breast tumors, RUNX1 downregulates Cx43 expression." (PMID 29701678, 2018).
cervical cancer (11 papers, 2015 to 2026). A primary or metastatic malignant neoplasm involving the cervix. "Moreover, network analysis showed that almost all genes that interacted with YAP, including other YAP-associated transcriptional factors such as ERBB4, Runx1, and Runx2, are up-regulated in various degrees in examined cervical cancer cases." (PMID 26417066, 2015). "An analysis of data from multiple databases confirmed the abnormally high expression levels of RUNX1 in cervical cancer." (PMID 38430423, 2024). "For example, in cervical cancer, RUNX1 overexpression was suggested to induce EMT and hence promote invasiveness of tumor cells." (PMID 38630262, 2024). "This modulation was similarly observed in cervical cancer, where elevated RUNX1 expression promoted EMT and markedly enhanced cancer cell invasion and metastasis." (PMID 39309442, 2024). "In cervical cancer, the RUNX1 expression level is abnormally elevated, promoting EMT and significantly enhancing the invasion and metastasis of cervical cancer cells." (PMID 38430423, 2024).
Obesity (11 papers, 2013 to 2025). Accumulation of substantial excess body fat. "Here, it is reported that peripheral nerve injury increases the expression of the m6A demethylase fat‐mass and obesity‐associated proteins (FTO) in the injured DRG via the activation of Runx1, a transcription factor that binds to the Fto gene promoter." (PMID 32670741, 2020). "However, the molecular roles that CDK6 and RUNX1 play in obesity and its associated metabolic diseases remains largely unexplored." (PMID 29523786, 2018). "Conversely, when mice were injected with EPO and RUNX1 inhibitors, they exhibited glucose intolerance and insulin resistance, and developed obesity." (PMID 39996752, 2025). "At the same time, EOMES-positive CD4 + T cells proved to be a risk T cell subset of RA; Studies have also discussed the molecular role of RUNX1 in obesity and related metabolic diseases." (PMID 35874719, 2022). "The hub genes CEBPD, TP73, ESR2, TAB1, MAP 3K5, FN1, UBD, RUNX1, PIK3R2 and TNF, which might play an essential role in obesity associated type 2 diabetes mellitus was further screened." (PMID 33902539, 2021). "Our findings indicate that CDK6 kinase activity negatively regulates the conversion of fat-storing cells into fat-burning cells by suppressing RUNX1, and suggest that CDK6 may be a therapeutic target for the treatment of obesity and related metabolic diseases." (PMID 29523786, 2018). "In the absence of CDK6 protein/kinase activity, RUNX1 is stabilized, BAT-specific protein expression is increased, and obesity and its related metabolic diseases are suppressed." (PMID 29523786, 2018).
osteoarthritis (10 papers, 2016 to 2025). A noninflammatory degenerative joint disease occurring chiefly in older persons, characterized by degeneration of the articular cartilage, hypertrophy of bone at the margins and changes in the synovial membrane. "Runx2 is an important pathogenic factor, while Runx1, Runx3, and Cbfb are protective factors in osteoarthritis development." (PMID 39337587, 2024). "We showed that chondrocyte-specific Runx1 knockout (Runx1f/fCol2a1-Cre) aggravated cartilage destruction by accelerating the loss of proteoglycan and collagen II in early osteoarthritis." (PMID 34876557, 2021). "Such a small molecule, kartogenin, binds to FLNA, disrupting its interaction with the transcription factor core-binding factor β subunit (CBFβ), and induces chondrogenesis by regulating the CBFβ-RUNX1 transcriptional program in osteoarthritis." (PMID 39195282, 2024). "In the current study, we aimed to explore the role of Runx1 in osteoarthritis induced by anterior cruciate ligament transaction (ACLT) surgery." (PMID 34876557, 2021). "This study helps us to understand the function of Runx1 in osteoarthritis and provides new clues for targeted osteoarthritis therapy." (PMID 34876557, 2021). "Although the molecular basis is currently unclear, Runx1 is a potential therapeutic target for osteoarthritis." (PMID 32079226, 2020). "RUNX1 abnormalities have also been found to be associated with non-hematological diseases, such as cardiovascular disease, osteoarthritis, and acute lung injury." (PMID 39151099, 2025). "In contrast to Runx2, Runx1 has been shown to exhibit opposite functions in osteoarthritis." (PMID 32079226, 2020). "Indeed, osteoarthritis phenotypes, including osteophyte formation and cartilage destruction, were reduced by injection of Runx1 mRNA in mice." (PMID 32079226, 2020). "We overexpressed Runx1 by adeno-associated virus (AAV) in articular cartilage and identified its protective effect by slowing the destruction of osteoarthritis in cartilage in early osteoarthritis and alleviating the pathological progression of growth plate cartilage in late osteoarthritis." (PMID 34876557, 2021). "Similarly, a compound was identified to inhibit osteoarthritis through upregulation of Runx1." (PMID 32079226, 2020). "Although the Runt-related transcription factor 1 (RUNX1) is well known for its role in skeletal development and other musculoskeletal related diseases such as osteoarthritis, its involvement in IDD pathogenesis remains elusive." (PMID 40932696, 2025).
renal fibrosis (10 papers, 2018 to 2026). A final common manifestation of a wide variety of chronic kidney diseases characterized by glomerulosclerosis and tubulointerstitial fibrosis. "Single-cell ATAC sequencing data further identified RUNX1 and its target genes in promoting fibroblast to myofibroblast differentiation, driving renal fibrosis." (PMID 40356603, 2025). "In a diabetic mouse model, miR-30b has been shown to improve renal fibrosis response by inhibiting renal Runx1 and Snail1 expression." (PMID 40242037, 2025). "•Ablation of RUNX1 in mouse RTECs inhibits renal fibrosis induced by unilateral ureteral obstruction or folic acid." (PMID 29759484, 2018). "Specific deletion of Runx1 in mouse RTECs attenuated renal fibrosis, which was induced by both unilateral ureteral obstruction (UUO) and folic acid (FA) treatment." (PMID 29759484, 2018). "To further determine the role of RUNX1 in renal fibrosis, we utilized another renal fibrosis model induced by folic acid (FA)." (PMID 29759484, 2018). "We found that RUNX1 promotes renal tubular EMT and that the deletion of RUNX1 specifically in RTECs significantly attenuated renal fibrosis." (PMID 29759484, 2018). "To better understand the effects of RUNX1 in TGF-β-induced EMT and renal fibrosis, we first examined the expression of RUNX1 in human renal tubular epithelial cell line HK-2 after stimulation with TGF-β." (PMID 29759484, 2018). "Deletion of RUNX1 in RTECs protected the host against renal fibrosis induced by unilateral ureteral obstruction (UUO) or treatment with folic acid (FA)." (PMID 29759484, 2018). "Here, we demonstrate that RUNX1 is overexpressed in the processes of TGF-β-induced partial EMT and renal fibrosis and that the expression level of RUNX1 is SMAD3-dependent." (PMID 29759484, 2018). "Furthermore, insufficient SIRT3 is functionally promote renal fibrosis by directly deacetylating RUNX1 at H4K12, leading to attenuated glycolytic process, and subsequently robust glycolytic ability and increased production of lactate." (PMID 41694585, 2026). "The increased expression levels of renal fibrosis-related genes (Grem2, Id3, Fst, Dcn) and renal damage-related genes (Runx1, Vtn, Clo6a2, Tnxb, Itga8, Timp2, Fgfr2, Fgf9) further supported the idea that miPEP31 deficiency exacerbated Ang II-induced kidney inflammation." (PMID 38992718, 2024). "Besides, it is also reported that RUNX1 plays an important role in regulating renal fibrosis by promoting TGF-β induced renal tubular epithelial-to-mesenchymal transition (EMT)." (PMID 37927796, 2023). "It is reported that RUNX1 can promote TGF-β-induced renal fibrosis through PI3K subunit p110δ." (PMID 37927796, 2023). "In this study, we used a conditional knockout mouse model that specifically deleted RUNX1 in proximal tubular epithelial cells and investigated whether and how RUNX1 mediated renal fibrosis and EMT." (PMID 29759484, 2018). "RUNX1 is mainly localized in RTECs in UUO-induced renal fibrosis." (PMID 29759484, 2018). "Importantly, ablation of Runx1 in mouse renal tubular epithelial cells or the RUNX1 inhibitor could reduce renal fibrosis in response to unilateral ureteral obstruction or under the treatment of folic acid." (PMID 29759484, 2018). "•These findings suggest that RUNX1 might be used as a potential target to prevent renal fibrosis." (PMID 29759484, 2018). "RUNX1 subsequently activated HK1 and SLC2A1, which accelerated glycolysis and renal fibrosis of DKD." (PMID 41694585, 2026). "Overexpression of RUNX1 has been shown to promote the expression of EMT marker genes in renal tubular epithelial cells and renal fibrosis." (PMID 34973136, 2023). "Previous studies have reported that RUNX1 interacts with HIF-1α and that HIF-1α promotes renal fibrosis via EMT." (PMID 29759484, 2018). "We used knockdown, overexpression and conditional KO mouse models to further demonstrate that RUNX1 is required for TGF-β-induced EMT and renal fibrosis in vivo." (PMID 29759484, 2018).